IL6 (interleukin 6)
Diseases named in the same sentence as IL6 in open-access papers (continued):
Sharing a sentence is not in itself a finding about the gene and the disease.
COVID-19 (continued). "Most COVID-19 patients showed normal thyroid function; however, the suppression of TSH is most likely related to elevations in pro-inflammatory cytokines such as IL-6, which are negatively correlated with TSH." (PMID 40735669, 2024). "Interactions between the five genes shared by all the investigated metals and COVID-19 (CXCL8, IL1B, IL10, IL6, and TNF) are mainly physical, whereas the dominant interaction between the genes affected by individual metals is co-expression." (PMID 38963144, 2024). "The increased expression of pro-inflammatory cytokines IL-6, IL-1β, and TNF-α in COVID-19 patients compared to the control group confirms the sequence of events following NF-κB activation." (PMID 39201618, 2024). "A progressive decrease in peripheral blood lymphocytes, an increase in IL-6, CRP, procalcitonin, and D-dimer are considered biomarkers for COVID-19 severity based on guidelines." (PMID 38601145, 2024). "Inflammatory biomarkers, such as IL-6 and CRP, are predictive biomarkers in COVID-19 patients and were significantly increased in the COVID-19-positive groups." (PMID 38799469, 2024). "Interleukins, such as interleukin-6 (IL-6) and tumor necrosis factor-alpha (TNF-α), play an important role in lung damage in COVID-19 patients through impairment of the respiratory epithelium." (PMID 39065742, 2024). "The findings from this investigation unveiled heightened plasma levels of key proinflammatory cytokines, including interleukin IL-1β, IL-6, TNF-α, monocyte chemoattractant protein-1, and soluble intercellular adhesion molecule-1 in COVID-19 patients." (PMID 38448675, 2024). "Biomarkers such as IL-6, IL-8, PAI-1, and ICAM-1, key to class designation in hyper- and hypo-inflammatory ARDS, were notably less class separating in severe COVID-19 subtypes, potentially rendering them less useful in phenotyping this patient population." (PMID 38383504, 2024). "Higher levels of cytokines such as IL-6, IL-10, and TNF-α were observed in patients with severe COVID-19 compared to those with a mild and moderate course of COVID-19." (PMID 39063142, 2024). "Most of the research focused attention on the first COVID-19 wave, in which high concentrations of IL-1β, tumor necrosis factor (TNF)-α, IL-6, IL-10, and interferon γ-induced protein (IP)-10 were observed in patients with severe forms of COVID-19." (PMID 39194742, 2024). "Total ANA titers were less important than BMI, initial disease severity and age in the prediction of ongoing PASC at 21–24 weeks after COVID-19 onset, but more important than sex and early levels of CRP, IL6 and IL10." (PMID 39008486, 2024). "The levels of cytokines, including IL-6, IL-1β, IL-10, IFN-γ, tumor necrosisfactor-α (TNF-α), and colony-stimulating factor (CSF), gradually increase with theseverity of COVID-19 and play a crucial role in the immune response to SARS-CoV-2 infection." (PMID 39759510, 2024). "Inflammatory markers, namely CRP, IL-6, LDH, and Ferritin, exhibited a significant elevation in COVID-19 cases as compared to the control group." (PMID 38464514, 2024). "Serum proteins like C-reactive protein, ferritin, D-dimer, procalcitonin, interleukin-6, serum creatinine, ALT, and AST remain to be promising tools for monitoring the prognosis and predicting the complications of COVID-19." (PMID 38378528, 2024). "It has been shown that some of the markers of COVID-19 deterioration and the development of acute respiratory distress syndrome include elevated LDH, CRP, IL-6, D-dimer levels, lymphocytes, platelets, renal function, and also high-sensitive troponin." (PMID 39768950, 2024). "The production of CRP by hepatocytes is stimulated by cytokines like interleukin‐6 (IL-6) and tumor necrosis factor-α (TNF-α) during COVID-19 development." (PMID 38184750, 2024). "It was observed that patients with severe COVID-19 had higher plasma levels of C-reactive protein (CRP), IL-6, and IL-8 compared to the patients with a mild–moderate course of the disease." (PMID 39063142, 2024).
COVID-19 (continued). "The biomarkers CRP, IL6, IP10, IL8, IL1RA, and suPAR showed good individual prognostic performance for severe COVID-19." (PMID 39664394, 2024). "One explanation to the higher rates of preterm delivery in women infected by COVID-19 is that the activation of pro-inflammatory mediators found in preterm delivery pathogenesis may share common pathways also in COVID -19 infection, such as macrophages or IL-6." (PMID 38709269, 2024). "DCs from healthy donors were stimulated with opsonized SARS-CoV-2 with serum from either mild or severe COVID-19 patients and induction of IFNβ, ISGs, such as IRF7, and IL-6 was measured." (PMID 38418557, 2024). "According to their worse COVID-19 condition, CAPA patients received more commonly anti-IL6 and monoclonal antibody [(9.1% vs 2.0% and 27.3% vs 5.1%, p = 0.02 and p < 0001), respectively]." (PMID 38605300, 2024). "Delivery of these complexes to uninfected mice boosts plasma interleukin-6 and CXCL1 levels as observed in COVID-19 patients." (PMID 38306481, 2024). "Surprisingly, HUVECs incubated with severe COVID-19 serum also showed a decrease in the expression of CCL2, IL6, TNFa, PTGS2, and ITGAM compared with the control that received or did not receive pretreatment with PC." (PMID 39066212, 2024). "Cytokine profiling of the sera of patients with COVID-19 and the transcriptional analysis of their BAL fluid revealed increased IL-6, G-CSF, CXCL10, CCL2, CCL3, and TNF-α levels, correlating with disease severity and progression." (PMID 39417078, 2024). "Among the various proinflammatory cytokines identified in individuals with COVID-19, TNF-α and IL-6 are present at higher levels compared to other cytokines." (PMID 39518964, 2024). "In severe COVID-19 patients, all CE species negatively correlated with CRP, 13 CE species with procalcitonin, 9 with IL-6, and 10 with ferritin." (PMID 39051245, 2024). "In the culture supernatant of PBMCs from healthy participants, bLf decreased IL-6 levels and increased CCL5 in COVID-19 participants." (PMID 39483459, 2024). "In terms of immune biomarkers, MSC treatment inhibited inflammation responses in COVID-19 patients, as was indicated by the decreased levels of CRP and IL-6." (PMID 38851730, 2024). "Interleukin (IL)-6 and tumor necrosis factor (TNF)-α have been considered by many as major cytokine culprits in the pathogenesis of this COVID-19-induced hyper-inflammation." (PMID 36445625, 2024). "Serum from both COVID-19 mild and severe patients suppressed IRF7 and IL-6 induction, which was restored by CD32/FcγRII inhibition." (PMID 38418557, 2024). "Several inflammatory markers, such as C-reactive protein (CRP), interleukin-6 (IL-6), neutrophil-to-lymphocyte ratio (NLR), and ferritin, have been identified as predictors of COVID-19 severity." (PMID 39767616, 2024). "In a retrospective clinical study (n = 80), oral supplementation with omega-3 PUFAs has significantly lowered proinflammatory procalcitonin and IL-6 levels and reduced prothrombin time in ICU/hospitalized COVID-19 patients." (PMID 38555403, 2024). "In contrast to IL-1β, IL-1Ra and IL-6 are generally secreted at higher concentrations and appeared elevated in both BALF and serum of COVID-19 patients." (PMID 39882243, 2024). "Regarding the biomarkers, in comparison with the patients with a mild course of COVID-19, the patients with a moderate/severe course had significantly elevated serum levels of CRP (p < 0.001) and IL-6 (p = 0.007)." (PMID 39518479, 2024). "The potential role of the inflammatory pathway in post-COVID-19 complaints is depicted by an increase in inflammatory markers, such as IL-6, fibrinogen, neutrophils, and C-reactive protein (CRP), in individuals with post-COVID-19 condition." (PMID 39056056, 2024). "In the current study, DPP3 was elevated in both endpoints of the COVID-19 cohort, but in ROC analysis, bio-ADM and IL-6 each had a higher AUC than DPP3." (PMID 38336628, 2024).
COVID-19 (continued). "One study showed that IL-6 ≥ 74.98 pg/mL, CRP ≥ 81 mg/L, PCT ≥ 0.56 ng/mL, and d-dimer ≥ 760 ng/mL effectively predicted the in-hospital mortality in COVID-19 patients." (PMID 38104038, 2024). "Cytokines such as interleukin-1 (IL-1), IL-6, IL-12, and tumor necrosis factor α (TNFα), some of which may be produced through mechanisms involving nuclear factor kappa B (NF-κB), likely contribute to the hyperinflammatory state in patients with severe COVID-19." (PMID 40012912, 2024). "In this sense, a systematic study showed that treatment with MT in a dosage of 5–25 mg/day favored a decrease in the inflammatory markers including IL-6, CRP, and TNF-α in the plasma of COVID-19 patients." (PMID 38674128, 2024). "Several immunomodulators agents, such as corticosteroids, interleukin-6 inhibitors (IL-6), and Janus kinase (JAK) inhibitors, have been investigated to treat hospitalized patients with COVID-19." (PMID 38350878, 2024). "IL-6 and MCP-1 were found at higher levels in both groups, whereas MCP-1, IFN-g and IL-18, stood out among those with increased production in COVID-19 patients, compared to the vaccinated individuals." (PMID 39258622, 2024). "IL-6, TGF-beta, and TNF-alpha are all cytokines that have been found to have connections with GSH and COVID-19." (PMID 38539805, 2024). "In a study involving 294 COVID-19 patients, the analysis revealed key post-COVID cytokines—FGF-2, VEGF-A, EGF, IL-12(p70), IL-13, and IL-6—crucial for understanding pathophysiology." (PMID 38793604, 2024). "IL-10, IL-6, MIP-1α, MCP-1, MCP-3, and TNF-α were significantly elevated in critical COVID-19 (OS7) compared to moderate COVID-19." (PMID 39494457, 2024). "COVID-19 patients also revealed a major increase in C-reactive protein (CRP), IL-2, IL-4, IL-6, IL-10, TNF-α, and IFN-γ." (PMID 38540252, 2024). "Eclitasertib also achieved numerically greater improvement in other inflammatory biomarkers including some of the markers of COVID-19 severity (leukocytes, neutrophil/lymphocyte ratio, LDH, IL-6, IL-8, and IL-6/IL-10) than placebo." (PMID 38419035, 2024). "This is an important finding suggesting that, although higher levels of IL-6 play a role in dropping circulating levels of fT3, the concomitant occurrence of low circulating fT3 and elevated IL-6 levels may have a synergistic effect on the deterioration of prognosis in COVID-19." (PMID 38243977, 2024). "In acute COVID-19, cGAS, STING, IFN-α, TNF-α, and IL-6 levels were higher in patients with severe disease than in those with nonsevere manifestations (p < 0.05)." (PMID 38424312, 2024). "In one study, it was noted that the activation of the innate immune system and cytokine storms (featuring elevated levels of TNF, IL-6, CXCL10, CCL2, CCL5, and IFN2) play crucial roles in the pathogenesis of COVID-19." (PMID 39685844, 2024). "Collectively, these findings suggest that our observations indicating that KO of ITGα5 in EVP reduces IM IL-6 levels and subsequently diminishes vascular permeability and the establishment of metastatic lesions, may have common implications in other diseases such as COVID-19." (PMID 38853850, 2024). "Many cytokines have been reported at elevated levels in COVID-19 cases, including IL1-β, IL-6, IL-7, IL-8, TGF-β and TNF-α." (PMID 38914619, 2024). "The positive regulator of IL6 signaling, OSM, was upregulated in lethal COVID-19 patients and SARS-CoV-2-infected patients with moderate compared to mild pneumonia." (PMID 38543303, 2024). "Compared with age-matched unexposed elderly individuals, convalescent COVID-19 patients presented with more IFN-γ and less IL-7, while IL-2, IL-6, IL-10, IL-12p70, IL-33 and CCL19/MIP-3 were unchanged." (PMID 38424104, 2024). "The NF-κB transcription factor is activated by cytokines such as IL-1β, IL-6 and TNF-α, which are elevated in severe COVID-19." (PMID 39051370, 2024).
COVID-19 (continued). "Multiple proinflammatory cytokines were found elevated in the sera of COVID-10 patients, among which are IL-1β, IL-6, and TNF-α, which correlated with COVID-19 severity and mortality." (PMID 38183501, 2024). "Many risk factors have been identified to be putatively relevant to the mortality of COVID-19, including older age, preexisting comorbidities, lymphocytopenia, C-creative protein (CRP), lactate dehydrogenase (LDH) and interleukin-6 (IL-6)." (PMID 38637771, 2024). "In particular, elevated levels of IL-6, IL-7, IL-10, IL-17, IL-23, TNFα, IFN-γ, IFNα or IL-1β have been found in severe COVID-19 cases and have already profoundly been analysed in recent Meta-Analysis." (PMID 38298642, 2024). "IL-6 and TNF-α are elevated in the blood and diseased tissue of patients with severe COVID-19 and are key cytokines for the development of cytokine storms." (PMID 38383655, 2024). "Other inflammatory pathways showed a mixture of upregulation and downregulation in the Malawian cohort compared to HLCA cohorts, including IL6/JAK/STAT (green arrow) and TNF-NFKB (blue arrow)—key targets for therapies being used in COVID-19." (PMID 39567718, 2024). "Dysregulation of immune response mediated by IL-6 induces an elevation of CRP and ferritin levels >800 μg/L, observed in patients with severe or fatal COVID-19." (PMID 38500972, 2024). "In this sense, IL-6 and CRP, which are pro-inflammatory molecules, were elevated in the serum of the COVID-19 patients in our study." (PMID 39057070, 2024). "Consistently, compared to non-COVID-19 group, the average values of SAA, hsCRP and IL-6 in ≥ 10 days COVID-19 group were all higher than that in < 10 days COVID-19 group." (PMID 38902401, 2024). "Other broadly acting immunosuppressives such as corticosteroids or more targeted modulation with IL-6 inhibitors (tocilizumab) and Janus-kinase (JAK) inhibitors (baricitinib) have now become standard of care for managing hyperinflammation in severe COVID-19." (PMID 39931105, 2024). "In mild-moderate COVID-19, the cytokine storm is similar to that observed in typical ALI and ARDS, with increased levels of proinflammatory cytokines such as IL-1β, IL-6, and TNF-α." (PMID 39130641, 2024). "Interestingly, CD32/FcγRII inhibition enhanced both type-I IFN and IL-6 responses compared to complement induction alone, which might be due to higher complement concentrations in serum from severe COVID-19 patients as suggested by higher opsonization of SARS-CoV-2." (PMID 38418557, 2024). "Regarding the composite endpoint ROC analysis showed an AUC of 0.89 for IL-6 and 0.83 for bio-ADM in COVID-19 patients." (PMID 38336628, 2024). "On the contrary, GABA-enclosed ADNVs displayed to profoundly suppress the expression of IL-6, a canonical proinflammatory cytokine that has been depicted as a signature of ARDS and a biomarker of cytokine storm characterizing severe COVID-19 pathologies." (PMID 38637808, 2024). "Inflammatory markers, notably C-reactive protein (CRP), interleukin-6 (IL-6), and erythrocyte sedimentation rate (ESR), have a positive correlation with COVID-19 severity." (PMID 38800223, 2024). "Patients with severe COVID-19 have been found to have elevated levels of various inflammatory markers in their blood, such as C-reactive protein (CRP), ferritin, interleukin-6 (IL-6), and others." (PMID 38814888, 2024). "Then, through an extended MR study design, we sought to strengthen the evidence for a causal relation of blood levels of IL-6 pathway components, including IL-6, sIL6R, soluble IL6ST (also called gp130), and CRP, on COVID-19 outcomes." (PMID 39062668, 2024). "In contrast to the control group, the COVID-19 T2DM groups exhibited a significant increase in PAR-1, NT-proBNP, HbA1c, IL-6, D-dimer, TNF-α, CRP, and homocysteine." (PMID 38675414, 2024). "Several clinical studies have postulated that cytokines (IL-1, IL-6, IL-8, and TNF-α) and chemokines were abnormally raised to high levels in COVID-19 patients." (PMID 38392902, 2024).
COVID-19 (continued). "Results showed that levels of IL-1β, IL-6, and TNF-α were significantly elevated after treatment with COVID-19 EVs." (PMID 39475319, 2024). "Regarding IL-6 and IFN-γ, similar findings have been reported from previous studies in COVID-19 patients." (PMID 38707035, 2024). "In moderate COVID-19 patients, IGFBP-2 levels were positively correlated with CRP, procalcitonin, LDH, AP, and IL-6, and negatively correlated with lymphocyte count." (PMID 38255230, 2024). "Targeted therapies, such as IL-1 and IL-6 inhibitors, show potential in managing ARDS, particularly in COVID-19, but their clinical efficacy is still debated." (PMID 39479463, 2024). "Despite these differences, prior research has consistently shown elevated inflammatory cytokines, such as IFN-γ, IL-10, IL-6, IL-8, CXCL10, MIP-1α, MIP-1β, TNF-α, and IL-17 in MIS-C patients compared to healthy controls and other pediatric COVID-19 cases." (PMID 39931580, 2024). "A slight decrease in serum FT4 and TSH levels was observed in 13% of 383 COVID-19 patients, consistent with NTIS, and increased pro-inflammatory cytokines, particularly IL-6, are negatively correlated with TSH levels." (PMID 40735669, 2024). "Moreover, while we included IL-6 in the scoring system due to its association with COVID-19 severity, this biomarker may not be universally accessible, as certain medical centers do not routinely measure it." (PMID 39594223, 2024). "In COVID-19, infection by SARS-CoV induces a dose-dependent production of IL-6 from bronchial epithelial cells." (PMID 38251210, 2024). "Enhanced TGF-beta signaling and increased NF-kB responses, as well as an increased expression of IL-6 and TNF-alfa, have been observed following COVID-19 vaccination." (PMID 39340046, 2024). "Since IL-6 and TNF-alpha are inflammatory cytokines that increase ROS, their upregulation in COVID-19 leads to increasingly depleted GSH and increasingly high ROS." (PMID 38539805, 2024). "Among COVID-19 pregnant patients AST, ALT and GGT > URL were positively correlated with inflammatory parameters (PCT, CRP and IL-6) and negatively with white blood count." (PMID 38166966, 2024). "A weighted gene co‐expression network analysis (WGCNA) of RNA-sequencing dataset revealed four key genes, PROK2, IL6, TNF, SLC7A11, closely related to COVID-19 ALI41." (PMID 38769293, 2024). "Patients with IL-6 levels >6.99 pg/mL and NLR >4.18 are 29 and 26 times more likely to suffer from severe COVID-19, respectively." (PMID 38099004, 2023). "Other studies, however, have demonstrated that the levels of IL-6, IFN-, and TNF in pediatric COVID-19 were stable and unchanged." (PMID 36839601, 2023). "Three cytokines/chemokines, IL-6, CXCL-10, and HGF, were found to be highly elevated in plasma samples of severe COVID-19 patients compared to mild/moderate patients." (PMID 37685858, 2023). "IL-6 and SAA were statistically different between the subgroups, i.e., they were significantly increased in patients with COVID-19." (PMID 38203482, 2023). "Patients with severe COVID-19, as evidenced in our study, release a large amount of pro-inflammatory cytokines (IFN-α, IFN-γ, IL-1β, IL-6, IL-12, IL-18, IL-33, TNF- α, and TGF- β)." (PMID 37408032, 2023). "The top ten anti-COVID-19 core targets, AKT1, TNF, HSP90AA1, IL-6, mTOR, EGFR, CASP3, HIF1A, MAPK3, and MAPK1, were chosen for molecular docking studies with the Meliae cortex’s key active phytonutrients determined in section 3.7." (PMID 36817449, 2023). "COVID-19 patients with ARDS exhibited higher serum levels of all cytokines and chemokines measured (IFNy, TNFa, IL-4, IL-6, IL-7, IL-8, IL-10, IL-13, MIP-1b, and MCP-1) compared to patients with COVID-19 pneumonia without ARDS (data not shown)." (PMID 37293294, 2023). "IL-6, CRP, NLR, PLR, glucose, AST, urea, creatinine, and eGFR were significantly higher in our severe/critical COVID-19 patients." (PMID 36838284, 2023).